IGF1 (insulin like growth factor 1)
Diseases named in the same sentence as IGF1 in open-access papers (continued):
Sharing a sentence is not in itself a finding about the gene and the disease.
respiratory disease (7 papers, 2015 to 2026). "HGF acts as a critical tissue-repair factor, and IGF1 regulates immune responses and cellular repair, with reduced levels associated with worsened outcomes in respiratory diseases including ARDS." (PMID 41200555, 2025). "The in silico analysis of this Igf1-driven subnetwork revealed organismal survival, organismal injury and abnormalities and, most importantly, respiratory disease as its major function." (PMID 29765129, 2018). "For both respiratory disease and umbilical infections, IGF-1 in the first week of life may be a good additional indicator to use for disease risk." (PMID 33540923, 2021).
skeletal dysplasia (7 papers, 2014 to 2024). Any Mendelian diseases that affects growth and development of the skeleton. "In humans and animal models, defects in any component of the GH/IGF-1 axis leads to a variable severity of postnatal growth failure (short stature) and skeletal dysplasia." (PMID 38241182, 2024). "The growth retardation and skeletal dysplasia phenotypes seen in Tmem263-KO mice strongly suggest a potential deficit in the GH/IGF-1 axis." (PMID 38241182, 2024). "PAPPA2 can play a role in normal development of children, and several rare dysfunctional mutations of PAPPA2, resulting in short stature and elevation of IGF1 levels as well as skeletal dysplasia, were reported in 2016." (PMID 34680885, 2021). "Together, these data indicate that low IGF-1, IGFBP3, and IGFALS levels likely contribute to growth retardation and skeletal dysplasia in Tmem263-KO mice." (PMID 38241182, 2024). "Additionally, various molecular defects in the Igf1 and Igf1r genes in humans have been associated with severe intrauterine growth retardation and impaired skeletal maturation, but not with truncated limbs or severe skeletal dysplasia." (PMID 24859417, 2014). "Consequently, Tmem263 knockout (KO) mice had low circulating IGF-1 and IGF binding protein 3 (IGFBP3), leading to dramatic postnatal growth failure and skeletal dysplasia." (PMID 38241182, 2024).
musculoskeletal diseases (6 papers, 2017 to 2025). "Chronically elevated GH and insulin-like growth factor-1 (IGF-1) levels lead to a complex spectrum of signs that include acral overgrowth, facial changes, musculoskeletal disease or gigantism if the GH hypersecretion occurs before epiphyses have fused." (PMID 28733467, 2017). "Taken together, IGF-1 plays a crucial role in the musculoskeletal system and decreased IGF-1 levels could result in musculoskeletal disorders and high fracture risk." (PMID 36010307, 2022). "Regenerative effects of SWT in musculoskeletal disorders are mediated by released TGF-β, insulin-like growth factor 1 (IGF-1) and bone morphogenetic proteins (BMPs)." (PMID 35647069, 2022).
benign tumors (5 papers, 2021 to 2024). "We also showed that BMR was related to benign tumors, and these associations were independent of IGF1." (PMID 34567085, 2021).
peripheral neuropathy (5 papers, 2010 to 2025). A disorder affecting the peripheral nervous system. "Spinal dorsal horn IGF1 contributes to the preventive effect of EA treatment against cisplatin-induced peripheral neuropathy through neuronal IGF1R signaling in mice." (PMID 41276799, 2025). "Consistent with our results, the antinociceptive action of IGF1 in the central and peripheral nervous system has also been proved in rats with peripheral tissue injury, and in mice with oxaliplatin-induced peripheral neuropathy." (PMID 41276799, 2025). "It has been reported that oxaliplatin reduces IGF1 level in the spinal cord, which may contribute to oxaliplatin-induced peripheral neuropathy in mice." (PMID 41276799, 2025).
hematologic cancers (4 papers, 2012 to 2023). "Our findings are consistent with previous reports of the ability of IGF-1 infusion to reverse the anticancer effects of CR in models of mammary, pancreas, bladder, and hematopoietic cancers." (PMID 23342276, 2012).
neuromuscular disease (4 papers, 2009 to 2024). "Many research groups have focused on using IGF-1 as a therapeutic option in neuromuscular diseases including DMD, given that IGF-1 has been shown to regulate muscle growth and function." (PMID 38189760, 2024). "The increase of KBs concentration, the reduction of blood glucose together with the involvement of many important pathways (e.g., IGF-1/AKT/mTor, AMPK/PGC1α) has shown to be a potential therapeutic weapon against many neurological and neuromuscular diseases." (PMID 25101284, 2014).
central nervous system disease (3 papers, 2019 to 2024). "In particular, the pivotal roles of cGP in regulating insulin-like growth factor-1 homeostasis, enhancing neuroprotective effects, and improving neurotrophic function in central nervous system diseases are described." (PMID 38921582, 2024).
infectious disease (3 papers, 2020 to 2024). A disorder directly resulting from the presence and activity of a microbial, viral, or parasitic agent in humans. "All of this provides substantial evidence that having low IGF-1 does indicate that a newborn calf is at increased risk of infectious disease and more studies are warranted to understand the main causes and consequences of reduced perinatal IGF-1 concentrations." (PMID 33540923, 2021). "Thirdly, the observed strongly significant association of higher plasma IGF1 levels with lower risk for infectious disease-related mortality may be interesting as well in this regard." (PMID 31973007, 2020).
mitochondrial disease (3 papers, 2017 to 2025). "Inhibition of insulin/IGF‐1 signaling (IIS) represents a promising avenue for the treatment of mitochondrial diseases, although many of the molecular mechanisms underlying this beneficial effect remain elusive." (PMID 30796049, 2019). "Involvement of the GH/IGF1 axis is well documented in mitochondrial diseases." (PMID 41480351, 2025). "It is also possible that S6K1 disruption is inducing changes in the signaling network through its regulation of the insulin/IGF-1 signaling network or additional targets, or that S6K1 disruption is alleviating mitochondrial disease in these animals by a mechanism distinct from rapamycin." (PMID 28919908, 2017).
dermatosis (2 papers, 2023 to 2026). "With the exception of IGF-1, there was general concordance between the profiles and independent biomarkers, with a striking lack of efficacy in determining hospitalisation for digestive, nervous, and skin disorders." (PMID 41542670, 2026).
gynecological diseases (1 paper, 2015). "Studies of CA repeats in the DNA of the P1 promoter of IGF-1 are ambiguous and controversial and do not apply to repeat CA gynecological diseases." (PMID 25384883, 2015).
IGF1 also shares sentences with these, for which no sentence is quoted: multiple myeloma (31 papers); hypertrophy (16); acute myocardial infarction (13); idiopathic pulmonary fibrosis (11); rhabdomyosarcoma (11); Parkinson’s (10); genetic disorder (9); gastrointestinal tumors (8); leishmaniasis (8); benign tumor of the pituitary gland (6); cerebellar ataxia (6); dysplasia (6); intestinal tumor (6); obstructive sleep apnea (6); small cell lung carcinoma (6); colorectal polyps (5); empty sella (5); Hearing impairment (5); metastatic cancer (5); ulcerative colitis (5); adrenocortical tumors (4); arteriosclerosis (4); craniopharyngioma (4); cryptorchidism (4); endometrial tumors (4); fibrosarcoma (4); Friedreich ataxia (4); gastrointestinal disease (4); Glomerular sclerosis (4); Hypercalciuria (4).
A further 400 diseases each share a sentence with IGF1 in 4 papers or fewer.